INS (insulin)
Diseases named in the same sentence as INS in open-access papers (continued):
Sharing a sentence is not in itself a finding about the gene and the disease.
insomnia (38 papers, 2011 to 2026). A sleep disorder characterized by difficulty in falling asleep and/or remaining asleep. "Nevertheless, they were also associated with higher risks of coronary atherosclerotic disease and insomnia compared to insulin and other agents, while showing a lower risk of hepatic failure." (PMID 40836299, 2025). "Other associated factors include an increased BMI of 1.26, serum triglyceride levels by 1.23 mmol/L, T2D risk by 2.07 times, fasting insulin by 1.14 pmol/L, insomnia rate by 53%, and visceral adipose tissue volume by 51%." (PMID 40041789, 2025). "CLOCK (Circadian Locomotor Output Cycles Kaput) is an important regulator of circadian rhythm, disruptions of which have been associated with pain, insomnia, insulin resistance, immunological function and impaired mitochondrial function." (PMID 37915075, 2023). "Regarding insulin levels, results showed significant associations between higher insulin and increased appetite, hypersomnia, insomnia and suicidal ideation." (PMID 37972981, 2023). "Insulin status also significantly affected the risk, with the highest risk of insomnia observed in the PDR group on insulin (aHR=1.293, 95% CI=1.221-1.369)." (PMID 35909567, 2022). "In the PDR group, a higher insomnia risk was observed in the group with a DM duration >5 years, insulin therapy group, and CKD group when compared with their counterparts." (PMID 35909567, 2022). "Furthermore, the reduction in slow-wave sleep caused by insomnia can lead to a reduction in insulin sensitivity, which is harmful to the dynamic balance of systemic glucose homeostasis." (PMID 39916567, 2025). "In healthy young and middle-aged adults with insomnia, physiologic hyperarousal has been associated with nocturnal insulin secretion and insulin resistance, as well as postabsorptive carbohydrate availability and increased fuel needs of glucose-dependent and glucose-independent tissues." (PMID 35910892, 2022). "This may underestimate the effects of night sweats on insulin resistance as night sweats frequently affect or interrupt sleep, leading to insomnia and cardiovascular risk." (PMID 28448547, 2017). "Forty adults with non-insulin-treated T2D and insomnia were randomized to CBTI (n = 20) or health education (HE, n = 20), delivered weekly via one-hour online sessions for eight weeks." (PMID 41114778, 2025). "In the current study, MR was performed to investigate the causal relationships of insomnia, sleep duration, short sleep duration, body fat percentage, VAT accumulation, T2DM, fasting glucose, and fasting insulin with GERD." (PMID 36895273, 2023). "Mendelian randomization analyses suggested potentially causal effects of BMI, body fat percentage, LDL cholesterol, total cholesterol, fasting insulin, income, insomnia, and childhood maltreatment." (PMID 37390107, 2023). "Based on the results of our study, these positive changes can relieve insomnia, much in the way that decreased waist circumference can reduce insulin resistance." (PMID 36673620, 2023). "By introducing core clusters for pathway analysis, it was found that the four Chinese medicinals played a therapeutic role in the ErbB signal pathway, cancer pathway, EGFR tyrosine kinase inhibitor resistance, and insulin signal pathway to treat insomnia." (PMID 35769674, 2022). "When the PDR status was considered, DM duration, insulin status, and CKD status all displayed significant interactive effects with PDR stage on the risk of insomnia." (PMID 35909567, 2022). "In the PDR group, sex, age, DM duration, insulin therapy status, and CKD status exerted interactive effects that increased the risk of insomnia." (PMID 35909567, 2022). "Over the last couple of years, numerous studies have suggested relationships between insomnia and decreased acute insulin reaction to glucose, glucose metabolism disorder, and insulin resistance, introducing it as a robust contributor to T2DM." (PMID 34869629, 2021).
insomnia (continued). "Insomnia is a potential factor behind weight gain, an observation that has been explained by altered leptin and ghrelin activity and higher glucose and insulin levels as well as an increased appetite." (PMID 30467691, 2019). "Moreover, insomnia probably influences the activity of hypothalamic-pituitary-adrenal axis, which leads to evening elevations of cortisol, and thereby affects insulin signalling and reduces insulin secretion." (PMID 39916567, 2025). "This relationship remained statistically significant and changed little when additionally controlling for sleep duration, sleep quality, insomnia symptoms, use of sleep medications, use of nervous medications, glucose, insulin, lipids, dietary energy intake, and C-reactive protein." (PMID 38956441, 2024). "Likewise, their work indicated several positive links between insulin and increased appetite, hypersomnia, and insomnia, as well as suicidal thoughts." (PMID 38980569, 2024). "In sum their work unraveled several symptom-marker connections between: higher metabolic markers and increased appetite; lower metabolic markers and decreased appetite; lower metabolic markers and insomnia; higher insulin and increased appetite; higher insulin and lower albumin and insomnia." (PMID 37972981, 2023). "However, a number of studies showed that the main clock genes (Bmal1, Clock, the Per family, Cry and others) function in various skin cells, and their work can be modulated by a number of additional factors (external light, UV light, feeding/insulin, sleep/insomnia etc.)." (PMID 37189753, 2023). "However, several of the proteins were shared among the models, including IL-29/IFN-L1 (pain duration and CPI), IL-12p70 and GRO-alpha (CPI and pain catastrophizing), ENA-78 (pain catastrophizing and perceived stress), and I-309 and pro-insulin (perceived stress and insomnia)." (PMID 35628904, 2022). "Chronic sleep restriction in rats induces metabolic dysfunction, increased plasma glucose, fasting insulin, lipids, insulin resistance and oxidative stress and decreases glucose tolerance; these parameters improve by treatment with piromelatine, a novel melatonin agonist, used for insomnia." (PMID 26166263, 2015). "Short or fragmented sleep, insomnia and hypersomnia—frequently observed across mood states—have been shown to alter HPA axis activity and appetite-regulating hormones such as cortisol, leptin and ghrelin, thereby increasing appetite, promoting weight gain and decreasing insulin sensitivity." (PMID 41590539, 2026). "In total, there were 105 SNPs as instrumental variables for insomnia, 36 SNPs for sleep duration, 14 SNPs for short sleep duration, 7 SNPs for body fat percentage, 136 SNPs for VAT, 100 SNPs for T2DM, 44 SNPs for fasting glucose, and 16 SNPs for fasting insulin." (PMID 36895273, 2023).
delirium (37 papers, 2017 to 2026). A disorder characterized by confusion; inattentiveness; disorientation; illusions; hallucinations; agitation; and in some instances autonomic nervous system overactivity. "It includes (A) scatter, (B) funnel, (C) forest, and (D) MR‐Egger plots to assess genetic effects, publication bias, effect estimates, and pleiotropy bias, evaluating the causal relationship between insulin and delirium risk." (PMID 40922636, 2025). "The study indicates that the levels of INS, BCL2L1, and IL‐7 in CSF may be linked to the risk of delirium, with INS playing a pivotal role." (PMID 40922636, 2025). "The aim of this study was to investigate the concentrations of metabolites related to insulin resistance and energy metabolism in the serum and CSF of patients with hip fracture, and to assess whether they were associated with delirium." (PMID 37658825, 2024). "In addition, abnormal glycemic traits, including fasting glucose (FG), fasting insulin (FI), and hemoglobin A1c (HbA1c) levels, have been reported to be associated with delirium." (PMID 36896238, 2023). "Preoperative intranasal insulin preconditioning is a potential strategy to prevent postoperative delirium (POD), but prior studies mainly used rapid-acting formulations." (PMID 41998765, 2026). "With ongoing research into dose optimization and systemic effects, central insulin delivery via the intranasal route holds promise as a novel approach for preventing and treating postoperative delirium in elderly patients." (PMID 41312480, 2025). "Based on this mechanistic rationale and evidence from chronic neurodegenerative diseases, researchers have begun investigating intranasal insulin for the prevention of acute postoperative delirium." (PMID 41312480, 2025). "Although statistical heterogeneity was low for most primary outcomes, differences existed in delirium assessment tools, insulin dosing, timing, and treatment duration." (PMID 41312480, 2025). "The results revealed a positive correlation between CSF INS and delirium (p = 0.01, odds ratio [OR] [95% confidence interval (CI)] = 1.35 [1.07–1.70])." (PMID 40922636, 2025). "Subgroup analysis was performed according to delirium scale, anesthesia method, type of surgery, dosage of insulin and age." (PMID 41312480, 2025). "For example, compared to placebo, perioperative intranasal insulin demonstrated a benefit with respect to post-operative cognitive performance and postoperative delirium in an older adult population undergoing elective surgery." (PMID 40253245, 2025). "Our study identified a genetic causal relationship between specific cerebrospinal fluid proteins and delirium, with insulin being a key factor." (PMID 40922636, 2025). "The efficacy and safety of intranasal insulin (INI) for preventing postoperative delirium (POD) remain uncertain." (PMID 41312480, 2025). "Abnormal glucose levels, a known risk factor for delirium, further underscore the role of insulin resistance in delirium development." (PMID 39754021, 2025). "Based on the data in this study, we propose that impaired glucose utilization occurs in the brain during delirium, with brain insulin resistance being a possible mechanism." (PMID 37658825, 2024). "Their findings revealed a significant reduction in cerebrospinal fluid insulin concentration among delirium patients, leading to the conclusion that preoperative insulin resistance exerts a profound influence on the occurrence of delirium." (PMID 38977983, 2024). ", meticulously quantifying insulin levels in the blood serum and cerebrospinal fluid of geriatric patients with hip fractures and delirium." (PMID 38977983, 2024). "Another theory for the development of delirium is decreased activity of the brain insulin signaling system, mainly due to central insulin resistance and insulin deficiency." (PMID 38523173, 2024).
delirium (continued). "This study aims to explore the genetic causal association between type 2 diabetes (T2D) and glycemic traits (fasting glucose [FG], fasting insulin [FI], and glycated hemoglobin [HbA1c]) on delirium using Mendelian randomization (MR)." (PMID 36896238, 2023). "In other mortality predictive studies in the literature, parameters such as functional status, steroid use, delirium, thrombocythemia, insulin use, and heart diseases have been evaluated, and they report that these parameters also contributed to mortality." (PMID 37308964, 2023). "Cox proportional hazard model showed that history of metformin use significantly decreased risk of 3-year mortality after adjustment for age, sex, CCI, BMI, history of insulin use, and delirium status (HR = 0.69, 95%CI: 0.48–0.98, p = 0.038)." (PMID 36399107, 2022). "Our proteomics analysis revealed that insulin may be elevated before surgery in the CSF of patients who develop delirium." (PMID 37759795, 2023). "Alterations in brain insulin sensitivity and metabolic function, increased blood-brain barrier permeability, neurotransmitter imbalances, abnormal microglial activation and neuroinflammation have all been involved in the pathophysiology of delirium." (PMID 38046817, 2023). "Systemic inflammation, neuroinflammation, alterations of brain blood flow, increased blood-brain barrier (BBB) permeability, impaired brain insulin sensitivity, and imbalances in neurotransmitter synthesis are the main mechanisms invoked as precipitating the onset of delirium." (PMID 38046817, 2023). "In addition, a higher proportion of patients in the Delirium group took diuretics (p = 0.003), insulin (p = 0.038), or psychiatric drugs (p = 0.003)." (PMID 32456289, 2020). "In the PPI network analysis, INS, BCL2L1, and IL‐7 were identified as central nodes, indicating their potential significant role in the pathophysiology of delirium." (PMID 40922636, 2025). "Median delirium duration [days (IQR)] was 4.8 [2.9, 9.2] for intranasal insulin and 6.8 [4.0, 9.8] for the control (HR 0.7, 95% CI 0.43-1.15; P = .16)." (PMID 41091693, 2025). "Larger nodes like INS, IL7, and BCL2L1 suggest central roles in the delirium pathway." (PMID 40922636, 2025). "Network analysis revealed several central nodes, including INS, BCL2L1, and IL‐7, which exhibited high connectivity, suggesting that these CSF proteins may play a central role in the pathophysiology of delirium." (PMID 40922636, 2025). "Individuals diagnosed with at least one delirium episode during hospitalization were treated with diuretics (p = 0.037) and insulin (p = 0.002) more often in comparison with non-delirious patients." (PMID 34279458, 2021).
end-stage renal disease (37 papers, 2007 to 2025). "As CKD progressed, metformin use significantly declined; insulin and meglitinides were most frequently prescribed in end-stage renal disease." (PMID 39459008, 2024). "Excess mortality from DM1 would have resulted from disruption in insulin supply, while CKD deaths could have arisen from various causes including missed haemodialysis sessions in patients with end-stage renal disease." (PMID 41299508, 2025). "Insulin purging in patients with AN/AAN and coexisting T1DM can exacerbate T1DM complications, including accelerating the onset of end-stage renal failure." (PMID 38152359, 2023). "Insulin and glucose homeostasis are altered in the patients of end stage renal disease and even in the early stages of CKD, leading to insulin resistance by a variety of pathways." (PMID 22935602, 2012). "As of the present, comprehensive treatment protocols and guidelines that offer the most effective treatment procedures for patients who exhibit insulin purging while having the co-occurrence of AN/AAN and T1DM, along with end-stage renal failure, are notably absent." (PMID 38152359, 2023).
glaucoma (37 papers, 2014 to 2026). Increased pressure in the eyeball due to obstruction of the outflow of aqueous humor. "Daily administration of human recombinant insulin eye drops stimulates dendrite and synapse regeneration in RGCs during ocular hypertension, a major risk factor for glaucoma, the leading cause of irreversible blindness worldwide." (PMID 41301488, 2025). "Our study suggests a novel role for Stim2 in the regulation of neuronal insulin expression and GABAergic-dependent vision causing glaucoma-like retinal pathology." (PMID 39424970, 2024). "Studying the insulin pathway in RGCs, glial cells, and endothelial cells and understanding the cross talk between insulin signaling and the various pathogenic events in glaucoma are essential to set the stage for future clinical investigations." (PMID 33925119, 2021). "In particular, patients treated with insulin were associated with higher risk of glaucoma." (PMID 38952394, 2024). "Impaired insulin signaling is associated with neurodegenerative diseases, including glaucoma." (PMID 39458902, 2024). "In addition, we found that diabetic patients treated with insulin (aHR = 1.884) were associated with higher risk of glaucoma compared to those treated with oral hypoglycemic agents (aHR = 1.449)." (PMID 34521935, 2021). "This may lead to systemic inflammation, and insulin resistance may promote microenvironmental perturbations that contribute to a predisposing milieu for elevated intraocular pressure or glaucoma." (PMID 27977733, 2016). "Preclinical studies in a mouse model of glaucoma have shown that human recombinant insulin delivered topically or systemically prevents RGC apoptosis and promotes neuroregeneration." (PMID 41584099, 2026). "Along with other strategies such as nicotinamide, recombinant human nerve growth factor, ciliary neurotrophic factor, and anticomplement C1q antibody, topical insulin has a strong scientific premise as a therapeutic for glaucoma." (PMID 41584099, 2026). "In this study, our primary focus is to evaluate the safety of topical insulin use in patients with glaucoma and examine the impact of insulin on both structural and functional measures." (PMID 41584099, 2026). "In a preclinical study demonstrating insulin neuroprotection in glaucoma mouse models, therapeutically delivered either by intraperitoneal injection or topically to similar effect, insulin-treated mice demonstrated larger and more complex dendrites." (PMID 41584099, 2026). "Research shows insulin supports neuronal survival, and abnormal insulin signaling has been observed in glaucoma patients." (PMID 41425077, 2025). "Growing evidence implicates metabolic dysregulation (particularly insulin resistance) in the pathogenesis and progression of glaucoma." (PMID 41054126, 2025). "Our data support that insulin is a compelling pro-regenerative strategy with potential clinical implications for the treatment and management of glaucoma." (PMID 39110798, 2024). "We then analyzed the distribution of PSD95-labeled synapses on dendritic processes, from the soma to the terminal, during glaucoma and after insulin treatment." (PMID 39110798, 2024). "We show that daily human recombinant insulin eye drops stimulate retinal ganglion cell (RGC) dendrite and synapse regeneration during ocular hypertension, a risk factor to develop glaucoma." (PMID 39110798, 2024). "Insulin treatment markedly improved visual acuity in mice with glaucoma relative to saline-treated controls, and this effect was sustained between 3 and 4 weeks of OHT." (PMID 39110798, 2024). "In patients with glaucoma, we anticipate that insulin will be used in conjunction with the standard care to lower IOP." (PMID 39110798, 2024). "A Phase 1 trial investigating topical insulin eye drops for glaucoma was conducted and showed safety in patients with glaucoma." (PMID 39458902, 2024).